ERBB2 (erb-b2 receptor tyrosine kinase 2)
Diseases named in the same sentence as ERBB2 in open-access papers (continued):
Sharing a sentence is not in itself a finding about the gene and the disease.
tumor (continued). "As genomic analysis revealed that the UCC14 patient tumor and paired PDX harbored a hotspot mutation in ERBB2 (HER2 S310F), we sought to leverage this model to explore the biological basis for the limited anti-tumor activity of HER2-targeted therapies in patients with UC." (PMID 32332851, 2020). "In addition, CD151-integrin complexes have been linked to tumor cell sensitivity to agents targeting ErbB2." (PMID 30778617, 2019). "The authors reported that ERBB2‐amplified tumors may benefit from anti‐HER2 therapy, and hypermutated tumors or tumors with high tumor mutational burden with MSI‐H or POLE mutation may benefit from anti‐PD‐1 therapy." (PMID 31127692, 2019). "The cell surface receptor HER2/neu, also known as ErbB2, is an important tumormarker and the best studied target for designing novel therapeutic agents,since it is overexpressed in many tumor types (including human breast cancercells) and is associated with the aggressive tumor phenotype." (PMID 30713766, 2018). "Besides breast and oesogastric carcinomas, 19 patients affected by 8 different tumor types had a CBR of 25% for ERBB2 mutations (n = 2/8, 95% CI 3%–65%, with 2 PR) and 64% for ERBB2 amplifications (n = 7/11, 95% CI 31%–89%; with 1 CR, 4 PR, 2 SD)." (PMID 29515767, 2018). "In conclusion, we have revealed ERK activity dynamics regulated by two distinct upstream receptors, EGFR and ErbB2, in the intestinal epithelium and shown that alterations in the dynamics caused by Wnt signalling activation underlie the high sensitivity of tumour cells to EGFR inhibition." (PMID 29872037, 2018). "Therefore, miR-3622b-5p is a tumor suppressor in ERBB2-positive cancers and a potential diagnostic marker and therapeutic target for human ERBB2-positive cancers." (PMID 28160563, 2017). "Moreover, p140Cap expression is advantageous for patient survival, strongly suggesting that p140Cap is still causal in limiting ERBB2 tumour aggressiveness within the complexity of the ERBB2 amplicon." (PMID 28300085, 2017). "Tumours found to harbour ErbB2 mutations may display addiction to ErbB2 signalling and sensitivity towards ErbB2 tyrosine kinase inhibitors." (PMID 28417948, 2017). "Two out of 36 frozen tumor samples harbored such ERBB2 mutations." (PMID 28636652, 2017). "Bertotti et al35 recently carried out exome sequence and copy number analyses of both patient‐derived xenografts and patient tumours, to investigate the effects of mutations in ERBB2, EGFR, FGFR1, PDGFRA and MAP2K1 in relation to resistance to anti‐EGFR therapies." (PMID 26690310, 2016). "In addition, Tiam1 associated with tumor stage and Ki-67 expression, but negatively correlated with receptor tyrosine-protein kinase erbB-2 (Her2) expression." (PMID 27562113, 2016). "On the other hand, activating PIK3CA mutations make the tumours refractory to ErbB2-targeted therapy, and the response may be restored by co-inhibition of PI3K." (PMID 27255951, 2016). "Further analysis of tumor cell-associated galectin-1 expression in ERBB2 tumors is therefore required to determine whether this is associated with poor prognosis." (PMID 26883193, 2016). "Thus, the amplification of chromosome 17q12-q21, which includes ERBB2, defines an intrinsic molecular cancer subtype associated with relatively aggressive tumour behaviour and poor clinical outcome." (PMID 27462779, 2016). "ERBB2 mutations may be of particular interest because the two tumors that include KRAS mutations also include ERBB2 mutations, and KRAS and ERBB2 are thought to function jointly to drive tumor growth." (PMID 25594743, 2015).
tumor (continued). "Tumor-associated antigens can be generated de novo or can arise from altered expression of normal basal proteins, such as the up-regulation of human epidermal growth factor receptor 2 (Her2/ErbB2)." (PMID 26334628, 2015). "Thus, among ∼20, 000 genes analyzed for expression levels, mRNA levels of ERBB2- and ESR1-related genes emerge as those crucial in mirroring tumor susceptibility to anti-HER2 therapy." (PMID 26334217, 2015). "In this study, we have identified increased macrophage infiltration within Luminal B and ERBB2 subtypes, and demonstrated that macrophage infiltration is associated with tumour recurrence, high grade and positive lymph node status which is consistent with previous published literature." (PMID 26008983, 2015). "We have previously reported that WAP-positive luminal epithelial cells are at increased susceptibility to tumor initiation by ErbB2 compared to the bulk population, while the mammary cells with canonical Wnt signaling activity fail to evolve into tumors upon ErbB2 activation." (PMID 25635772, 2015). "Finally, we showed that PKD1 expression does not correlate with classical clinical and pathological prognostic factors (SBR histological grade, macroscopic tumour size, PR and ERBB2 statuses and PIK3CA mutation status)." (PMID 25287328, 2014). "Thus, in the tumour tissue, ErbB2-IR scores are associated with the downstream signalling molecule pAkt and with the cell proliferation marker Ki67, but not robustly with the clinical measures of disease severity." (PMID 25215939, 2014). "However, when ordinal regression analyses including the Ki67 index into account were undertaken, a significant interaction between AR-IR and ErbB2-IR with respect to their association with the tumour stage was found." (PMID 25215939, 2014). "Activation of RTK signaling caused by HRG-associated heterodimerization of ErbB3 and ErbB2 may be a critical step in tumor progression." (PMID 23937725, 2013). "HIF-1α is highly expressed in human cancers as a result of intratumoral hypoxia as well as genetic alterations, such as gain-of-function mutations in oncogenes (for example, ERBB2) and loss-of-function mutations in tumour-suppressor genes (for example, VHL and PTEN)." (PMID 23382894, 2013). "In this report, we tested whether Wnt signaling-active mammary epithelial cells are more or less susceptible to tumor induction by aberrant ErbB2 signaling than other cells in the mammary epithelium." (PMID 24265712, 2013). "Loss of steroid receptor and Foxa1 expression in MMTV-NeuNT tumors indicated that Erbb2 expression drove the loss of these markers and that their loss may be associated with tumor etiology." (PMID 23593223, 2013). "Moreover, we previously found that decreased PTPN13 expression synergizes with an activated ErbB2 transmembrane mutation (mNeuNT) enhancing tumor growth and invasion in vivo." (PMID 22279592, 2012). "To test this possibility, we explanted two independent cell lines from the parental MMTV-NDL2-5 tumours and from ErbB2 induced tumours carrying both conditional FAK alleles (NDL2-5/FAKflx/flx) and infected them with empty vector controls or retroviral vectors expressing Cre recombinase." (PMID 22373082, 2012). "Cytoplasmic ERBB3 was associated with high tumour grade (P=0.01) and with ERBB2 positivity." (PMID 21364580, 2011). "Similar to the basal-like tumours, overexpression of the ERBB2 oncogene was associated with low ER." (PMID 20520800, 2010). "Thus, we found that Amplicon Class with TOP2A deletion in ERBB2-amplified BC was associated with shorter time to tumor recurrence and significantly higher risk of cancer recurrence independent of other covariates." (PMID 18702822, 2008).
tumor (continued). "As novel HER2-targeting regimens enter clinical practice and more patients with ERBB2-mutated tumors are eligible for targeted therapy, the need arises to further understand the evolution of the mutational landscape in the trajectory from diagnosis to refractory disease in different tumor types." (PMID 40770324, 2025). "Tumor cells with PIK3CA mutations are resistant to drugs targeting epidermal growth factor receptor (EGFR) or erythroblastic leukemia viral oncogene homolog 2 (ERBB2), but may be more sensitive to mTOR and PI3K inhibitors." (PMID 41040523, 2025). "Besides, another team has established human NK-92 cells that could recruit them to the tumor associated ErbB2 (HER2) antigen." (PMID 40052147, 2025). "We developed highly sensitive multiplex digital PCR assays to detect and quantify ERBB2 mutations in circulating tumor DNA from liquid biopsies and found mutations in 3.3% of 272 patients with hormone‐receptor‐positive, human epidermal growth factor receptor 2‐negative (HR+/HER2−) MBC." (PMID 38287892, 2024). "Interestingly, in an exhaustive meta-analysis of 37,218 patients, including 11,906 primary tumor samples, 5,541 extracerebral metastasis samples, and with 1485 brain metastasis samples found that a nearby ERBB2 mutation (P1227S) was the only mutation restricted to brain metastasis." (PMID 38650031, 2024). "Taken together, these observations suggest that all the ERBB3 variants can be targeted in ERBB3/ERBB2 heterodimeric complexes with anti-ERBB antibodies or TKI’s but that the sensitivity may depend on the availability of activating ligands in the tumor microenvironment." (PMID 38806620, 2024). "Interestingly, vascularization seems to depend on tumor type (luminal, basal, or metastatic) while vascular permeability and response to normalizing interventions seem to be associated with the expression of HER2/ERBB2 and EGFR." (PMID 39041892, 2024). "Meanwhile, the additional GEO datasets showed that the expression of ERBB2 in TNBC was significantly positively correlated with M0 macrophages infiltration but negatively associated with the M1 macrophages infiltration which play an important role in in anti-tumor immune activities (P < 0.001)." (PMID 36998014, 2023). "Moreover, in UTUCs with ERBB2 amplification or gain, significant associations with higher tumor grade, invasion, advanced stage, distant metastasis, positive lymph node status, and positive ERBB2 immunoreaction according to both evaluation schemes were demonstrated." (PMID 37173881, 2023). "Additionally, pharmacological NRF2 induction by CDDO-Me significantly reduced the rate of tumour development in breast cancer-associated gene 1 (BRCA1)-deficient mice through the knockdown of ErbB2 protein expression, a known oncogene, with direct modification of ErbB2 cysteine residues." (PMID 37047696, 2023). "The three main tumor subtypes of BC, characterized by ER or PR expression and amplification of the ERBB2 gene, have different risk characteristics and treatment strategies, with the optimal treatment for each patient depending on the tumor subtype, anatomic tumor stage, and patient preference." (PMID 35720010, 2022). "The authors indicated that this high proportion of ERBB2 mutations in HR-positive patients indicates the need to assess for resistant mutations in this population and highlighted the current limitation to detect CNAs in ctDNA due to the very low tumour fraction found in plasma." (PMID 35158855, 2022). "Moreover, ErbB2-positive tumors contain numerous mutations that differ between patients and could also affect tumor BLNK levels and disease progression." (PMID 35933456, 2022).
tumor (continued). "Importantly, tumour formation in this system was associated with Erbb2/NeuNT locus amplification by an unknown mechanism." (PMID 34003256, 2021). "Moreover, ERBB2 was overexpressed in 29.1% (16/55), 80% (60/75), and 82.4% (28/34) of patients with ECC, and ERBB2 is closely associated with tumor grade, higher rates of distant metastases, and poor survival of ECC patients with lymphatic invasion and perineural invasion." (PMID 32708604, 2020). "Thus, ERK activity dynamics are defined by composite inputs from EGFR and ErbB2 signalling in IECs and their alterations might underlie tumour-specific sensitivity to pharmacological EGFR inhibition." (PMID 29872037, 2018). "Thus, we speculated that increase in the cancer cell density within a three-dimensional tumor mass can block the activity of Mek or that of its substrates and cause inhibition of ErbB2 expression." (PMID 29285258, 2017). "However, the association between tumour ErbB2-IR and pAkt-IR remained significant." (PMID 25215939, 2014). "In addition, ErbB2 has been implicated in tumor pathogenesis and progression." (PMID 24069396, 2013). "The pathway analysis indicated alterations in PI3K/Akt, MYC and NF-κB signaling pathways, and potential critical roles for TGFA, ErbB2, and IL-1/IL-1R which may promote angiogenesis, tumor growth, and metastasis and hence cause the aggressive phenotype observed in young women." (PMID 23704896, 2013). "We hypothesised that co-targeting the preferred ErbB2/ErbB3 heterodimer with a bispecific single-chain Fv (bs-scFv) antibody would promote increased targeting selectivity over antibodies specific for a single tumour-associated antigen (TAA)." (PMID 18841159, 2008). "We therefore submit that human tissues with cell-cycle control defects may gain a growth advantage by prolonging and intensifying ambient growth factor signals via ErbB2 upregulation, and that tumour cells overexpressing ErbB2 may in turn clonally select for cell-cycle checkpoint loss." (PMID 11953857, 2002). "In the ctDNA substudy (n = 14), methylation-derived tumour fraction declined during therapy and ERBB2 plasma copy number gain aligned with tissue HER2 status." (PMID 42087741, 2026). "IL-6 and B-cell lymphoma 2 showed downregulated expression in tumor tissues, while cyclin-dependent kinase 1, cyclin-dependent kinase 2, cyclin B1, Erb-B2 receptor tyrosine kinase 2, and cyclin B2 were upregulated." (PMID 41650055, 2026). "Advanced age at diagnosis is associated with more favorable biological factors, such as high hormone receptor (HR) expression, decreased Human Epidermal Growth Factor Receptor 2 (HER2/c-erbB2) overexpression, low tumor grading, and low proliferative index." (PMID 40647368, 2025). "ERBB2 i14e was inducible and its expression attenuated anti-ERBB2 treatment efficacy in tumor xenografts." (PMID 39948369, 2025). "Surveying the Xenium probe-based in situ sequencing and imaging data, we found high agreement between three cell type markers (ERBB2-tumor, PTPRC-immune, and PDGFRA-stroma) and our CTA outcomes, suggesting its robustness for detecting FFPE sections as well." (PMID 40925915, 2025). "Despite the promising results of trials, a significant challenge remains in identifying HER2-positive tumors among tumor types that lack routine ERBB2 (HER2) testing." (PMID 40828885, 2025). "To assess 929-B6-mediated targeting in vivo, we conducted a pilot experiment in mice bearing ERBB2-positive tumor xenografts." (PMID 41472234, 2025). "In vivo imaging of ERBB2+ tumors revealed a visible tumor-localized luminescent signal following administration of 929-B6-treated vectors." (PMID 41472234, 2025).
tumor (continued). "Treatment with an autophagy-inducing peptide, Tat-BECN1, overcomes the tumor growth and inhibitory effect on autophagy of deregulated receptor tyrosine kinases, such as HER2/ERBB2." (PMID 40754831, 2025). "ERBB2 co-amplification was seen in three additional cases: an IHC 1+ tumor harboring an Ex20Ins (P780_Y781insGSP), an IHC 1+ tumor with G776V, and an IHC 2+/FISH- tumor with V777L." (PMID 40178042, 2025). "HER2 expression can also be identified through the sequencing of tumor tissue, noted as ERBB2 amplification." (PMID 40507303, 2025). "Further features, such as NF1 loss, MAP2K1 mutations, ERBB2 activation, and frequent copy number changes (including CDKN2A/2B deletion and 1p/1q imbalances), add to tumor heterogeneity and evolution." (PMID 41376748, 2025). "Sudhan and colleagues further demonstrated that treatment with everolimus, an mTOR inhibitor, was able to overcome resistance by restoring ErbB2-mutant tumor cell sensitivity to neratinib." (PMID 39908697, 2025). "Tissue CGP plausibly yields higher detection rates for TMB-high and ERBB2 amplification because plasma assays are intrinsically constrained by circulating tumor fraction (ctF) and by the physics of cfDNA." (PMID 41008912, 2025). "These CAR-CIK cells demonstrated superior specificity and cytotoxicity against ERBB2-positive tumor cells compared to wild-type CIK cells." (PMID 41007114, 2025). "To corroborate these findings, we injected ERBB2 KO tumor cells orthotopically into immunocompetent mice." (PMID 41361170, 2025). "Another intriguing finding was the limited ability of ESRP1 to induce i14e splicing in non-cancerous gallbladder epithelial cell line (L-2F7), which suggests other tumor-intrinsic factors are also involved in ERBB2 i14e splicing." (PMID 39948369, 2025). "Systemic therapy use, however, can be dependent on molecular characterization, such as HER2 expression status and mutational status of ERBB2, PIK3CA, AKT1, PTEN, and ESR1, particularly in the primary tumor." (PMID 41149070, 2025). "The observed rapid and durable tumor regression aligns with preclinical evidence showing T-DXd’s robust efficacy in ERBB2-amplified xenograft models." (PMID 40969261, 2025). "We sought to define the pan-tumor landscape of activating ERBB2 and ERBB3 genomic alterations detected by comprehensive genomic profiling (CGP)." (PMID 40178042, 2025). "CAFs can transfer oncogenic molecules, such as miRNAs and proteins, via exosomes, further contributing to resistance in genomically distinct subtypes, including ERBB2-amplified tumours." (PMID 40861435, 2025). "The excessive activation of HIF1α in cancer, despite oxygen availability, is often driven by oncogenes (e.g., ERBB2, PI3K, Ras, protein kinase B/AKT, mTOR) and mutations in tumour suppressors (e.g., Von Hippel–Lindau (VHL) and PTEN)." (PMID 41007296, 2025). "RNA-seq analysis of PDXs following treatment demonstrated ERBB2 i14e suppression was correlated with reduced tumor cell proliferation, enhanced apoptosis, and altered cellular redox state." (PMID 39948369, 2025). "ERBB2 (HER2) alterations (eg, overexpression, amplification, and mutations) are known to drive tumor progression." (PMID 40828885, 2025). "Its downregulation is linked to increased tumor aggressiveness, enhanced EMT, and metastatic potential via upregulation of ERBB2 and L1CAM expression." (PMID 40805172, 2025). "This is due to its role in promoting HER2/Neu (ErbB2)-mediated signalling that promotes tumor cell proliferation." (PMID 41286812, 2025). "HER2 overexpression,primarily attributed to ERBB2 gene amplification, has been identified inbreast, gastric, pancreatic, lung, endometrial, ovarian, bladder, colorectalcancer, and various other tumor localizations." (PMID 41479565, 2025).